ORMDL3 (ORMDL sphingolipid biosynthesis regulator 3)
Diseases named in the same sentence as ORMDL3 in open-access papers (continued):
Sharing a sentence is not in itself a finding about the gene and the disease.
asthma (continued). "Additionally, hypomethylation at the ORMDL3 and GSDMB loci within the 17q21 asthma susceptibility region has been observed in children with early-onset asthma and rhinovirus-related wheezing, underscoring their potential in risk prediction and personalized treatment planning." (PMID 40806756, 2025). "Notably, the expression of ORMDL3 (encoding ORMDL sphingolipid biosynthesis regulator 3) and GSDMB (encoding gasdermin B), both asthma-associated genes located in the 17q21 locus, was significantly elevated in RV-stimulated peripheral blood mononuclear cells (PBMCs) compared to unstimulated PBMCs." (PMID 40806756, 2025). "The contribution of ORMDL3 expression to risk of childhood asthma is less clear, with transgenic mice showing airway remodelling consistent with asthmatic disease and no impact of ORMDL3 expression on asthma responses in allergen tests." (PMID 39170919, 2024). "Therefore, GSDMB, PGAP3, and ORMDL3 are the leading candidate asthma genes." (PMID 37064151, 2023). "However, the mechanistic contribution of ORMDL3 to the pathogenesis of asthma remains unclear and experimental evidence suggests the relationship between ORMDL3 and asthma is complex." (PMID 36206293, 2022). "Examples of pathways or networks that are implicated by GWASs in asthma are the IL33-IL1-RL1 receptor pathway, leading to eosinophilia, and the T-helper-2 (Th2) cytokine IL-5 and IL-4RA receptor, leading to eosinophilia and type 2 inflammation or viral response (CDHR3, ORMDL3)." (PMID 35656293, 2022). "However, the role of ORMDL3 in ER driven asthma pathology remains to be resolved." (PMID 35386986, 2021). "As ASM hypertrophy is a feature of asthma, we investigated whether ORMDL3 expression in ASM influenced hypertrophy by measuring both cell size by FACS and ASM protein to DNA ratio (an index of cell hypertrophy) and by image analysis in ASM derived from hORMDL3Myh11eGFP-cre and WT mice." (PMID 33661765, 2021). "Moreover, the expression of ORMDL3 (encoding ORMDL sphingolipid biosynthesis regulator 3) and of GSDMB (encoding gasdermin B), the 17q21 genes related to asthma, was significantly higher in RV-stimulated compared to the unstimulated peripheral blood mononuclear cells (PBMCs)." (PMID 33668787, 2021). "In mice, ORMDL3 expression has been shown to be induced by allergen, IL-4 and IL-13 via STAT6 and in bronchial epithelial cells, overexpression of ORMDL3 has been shown to trigger activating transcription factor 6 (ATF6), which has also been implicated in airway remodeling in asthma." (PMID 35386986, 2021). "Although the potential contribution of ORMDL3 to asthma pathogenesis has been described and it might influence airway hyperreactivity, sphingolipid synthesis, and allergic response, there is a lack of studies especially addressing its predictive role on the risk of exacerbations." (PMID 33925009, 2021). "However, the definite role of ORMDL3 in the pathogenesis of asthma remains unclear and needs further analyses." (PMID 33971943, 2021). "Thus, children with SNPs linked to chromosome 17q12-21 and increased expression of ORMDL3 in ASM may develop a childhood onset increased thickness of the ASM layer, predisposing to the development of childhood onset asthma." (PMID 33661765, 2021). "ORMDL3 expression in ASM thus induces changes in ASM (hypertrophy, hyperplasia, increased contractility), which may explain the contribution of ORMDL3 to the development of AHR in childhood onset asthma, which is highly linked to ORMDL3 on chromosome 17q12-21." (PMID 33661765, 2021). "Additionally, ORMDL3, which is predominantly expressed in AECs, is strongly associated with AHR, as well as airway remodeling, inflammation, and mucus hypersecretion, in other allergen-models of asthma." (PMID 34122136, 2021).
asthma (continued). "These mixed results arguably emphasize a separate unanswered question as to which cells exhibiting heightened ORMDL3 expression may be most relevant in driving asthma pathology, and whether functional abnormalities are primarily driven by altered sphingolipid biosynthesis in specific cells." (PMID 33424845, 2020). "Changes in ORMDL3-dependent regulation of the SERCA pump could elicit ER stress and UPR in multiple cell types, including CD4+ T cells, contributing to increased incidence and/or severity of asthma in patients with 17q12–21 risk SNPs." (PMID 33424845, 2020). "In the lung, ORMDL3 activates the UPR via the ATF6 pathway, increasing transcription of endoplasmic reticulum–associated protein degradation pathway-specific genes (Edem-1) and regulating the expression of IL-6, which has been implicated in the pathogenesis of asthma." (PMID 27623174, 2017). "Furthermore, it might be that unknown environmental influences affect the relationship of ORMDL3/GSDMB with asthma, which may explain the difference between our findings and those of others." (PMID 25768087, 2015). "Thus, ORMDL3 high-expression may also contribute to airway remodeling in patients suffering from asthma or mice model sensitized with allergen." (PMID 23577138, 2013). "However, the functional role ORMDL3 in the pathogenesis of asthma has yet to be elucidated." (PMID 23369242, 2013). "ORMDL3 has so far been thought to be the most promising candidate at this locus, since it has a role in mediating inflammation, and also has expression in bronchial epithelial cells, where slightly higher ORMDL3 expression was found in individuals with asthma compared to controls." (PMID 24044605, 2013). "Whether or not ORMDL3 is the causal gene responsible for predisposition to asthma remains to be addressed using other approaches." (PMID 22271045, 2012). "ORMDL sphingolipid biosynthesis regulator 3 promoted angiogenesis through upregulating vascular endothelial growth factor and MMP9 in asthma airway remodeling." (PMID 41150507, 2025). "Few studies have specifically addressed ORMDL3's predictive function on the likelihood of exacerbations, although it may have a role in airway hyperreactivity, sphingolipid production, and allergic reaction, all of which may be related to its possible contribution to asthma pathogenesis 23,40." (PMID 40104184, 2024). "Mouse models have contributed to our understanding of ORMDL3 function as mice expressing the ORMDL3 transgene exhibit spontaneous increases in airway hyper responsiveness (AHR), the essential feature of asthma." (PMID 38567749, 2024). "With regard to commonly differentially expressed genes we found ORMDL3 to be downregulated in the blood of both PTSD and severe asthma subjects." (PMID 36206293, 2022). "Most markedly, the “17Q12-21” locus, which has been simulated in numerous GWASs and harbors numeral probable biologic candidate genes, comprising ORMDL3 and GSDMB, has been concerned in the development of asthma." (PMID 36225476, 2022). "CTCF was also found to be recruited in asthma risk-related SNPs of the ORMDL3 gene and increased the activity of its enhancer in naïve CD4 T cells, which was essential for the repression of Il2 expression in the same cell type, a mechanism that may contribute to asthma progression." (PMID 35812421, 2022). "For example, we showed that one of the candidate genes in the core region, ORMDL3, is downregulated by RV in cultured AECs, and that an eQTL for ORMDL3 colocalizes with a meQTL in a neighboring gene, GSDMB, and with a TAGC asthma GWAS SNP." (PMID 34629083, 2021). "This study also demonstrated the importance of TPM to ORMDL3-induced ASM proliferation, which can manifest as ASM hyperplasia in the airway in asthma." (PMID 33661765, 2021).
asthma (continued). "In addition to demonstrating that ORMDL3 expression in ASM induced functional changes (i.e., increased ASM hypertrophy, proliferation, and contractility), we identified potentially novel pathways through which ORMDL3 may contribute to these ASM changes characteristic of asthma." (PMID 33661765, 2021). "Expression levels of HLA-DQA1/A2 (P = 0.0077), ORMDL3 (P = 0.0021), and RORA (P = 0.0005) were significantly lower in severe asthma subjects only compared to controls." (PMID 35386986, 2021). "One of the other key cells that is present in the lung in asthma, but not present in the upper airway in allergic rhinitis, is ASM, whose expression of ORMDL3 may help explain the epidemiologic association of chromosome 17q21-21 with childhood onset asthma but not allergic rhinitis." (PMID 33661765, 2021). "Thus, it may be that enhanced ORMDL3-dependent modulation of sphingolipid synthesis in CD4+ T cells results in improper allergic or neutrophilic inflammatory responses across the clinical spectrum of asthma phenotypes." (PMID 33424845, 2020). "This previous study identified genes on chromosomes 2 (IL1RL1/IL18R1), 6 (HLA-DQ), 9 (IL33), 15 (SMAD3), 17 (ORMDL3/GSDMB), and 22 (IL2RB) correlated with asthma." (PMID 32512817, 2020). "From these findings, we might hypothesize that in patients carrying 17q12–21 asthma risk SNPs, dynamic changes in the expression and action of key ER SERCA pumps in response to T cell receptor (TCR) activation would be hindered by higher ORMDL3 expression in CD4+ T cells." (PMID 33424845, 2020). "Moreover, a recent study from the Worgall group quantified sphingolipids in plasma and whole blood samples in children with or without asthma, linking 17q21 SNPs associated with elevated ORMDL3 expression to lower circulating sphingolipid species (e.g. ceramides)." (PMID 33424845, 2020). "Collectively, these findings suggest a plausible mechanism connecting changes in ORMDL3 expression to the UPR, ER stress, and inflammation that warrants more exploration in the context of asthma." (PMID 33424845, 2020). "With perhaps one exception, ORMDL3-dependent SPT regulation has been demonstrated in many cell types over several different studies, presenting a reasonable hypothesis that sphingolipid dysregulation could contribute to asthma pathophysiology in patients with the 17q12–21 risk SNPs." (PMID 33424845, 2020). "Interestingly, FTY720 reduced the ORMDL3 expression, AHR and associated inflammation, and mucus production and elevated the ceramide levels in house dust mite-induced lung inflammation model in mice, further confirming the potential beneficial role of FTY720 in the treatment of asthma." (PMID 28352271, 2017). "They reported that in vitro overexpression of ORMDL3 activated the ATF6 pathway of the UPR and induced expression of several genes with potential importance in the pathogenesis of asthma." (PMID 23369242, 2013). "In type 2-high, type 2-low, and obesity-related asthma endotypes, chronic hypoxia, HIF-1α stabilization, ORMDL3-ceramide signaling, and systemic metabolic stress converge to induce highly glycolytic, Th2/Th17-polarizing DCs in a lactate-rich, acidic microenvironment." (PMID 42004956, 2026). "Other genes within this locus, including ORMDL3 and GSDMB, have studies not only demonstrating their genetic epidemiologic linkage to asthma, but also studies of their biology implicating them in the pathogenesis of asthma and airway remodeling." (PMID 40131902, 2025). "Protein kinases, adapter protein, microRNAs, ORMDL3, and gasdermin B are newly identified molecules that drive asthma progression, independent of inflammation." (PMID 36078171, 2022). "Protein kinases, adapter protein, miRs, ORMDL3, and gasdermin B are newly identified molecules that contribute to asthma pathogenesis, independent of inflammation." (PMID 36078171, 2022).
asthma (continued). "It should be noted that in our studies the ORMDL3 mRNA copy number in mouse ASM we studied, which was derived from hORMDL3Myh11eGFP-cre mice, was similar to the hORMDL3 copy number detected in ASM from human patients with asthma." (PMID 33661765, 2021). "This suggests that ORMDL3 expression in ASM can lead to altered gene expression of selected genes (SERCA2b, SM22) known to be involved in smooth muscle cell contraction, a feature of asthma." (PMID 33661765, 2021). "Multiple GWAS and functional studies relate asthma to ORMDL3 and GSDMB however to our knowledge no studies have been published investigating this variant or linked genes with regards to neutrophils in asthma." (PMID 35386986, 2021). "In addition to THSD4 and HIVEP2, age-by-genotype interactions also prioritized genes previously identified as asthma candidate genes, including DPP10, HDAC9, TBXAS1, FBXL7, and GSDMB/ORMDL3, as pharmacogenomic loci as well." (PMID 32119686, 2020). "Employing this approach, Ober and colleagues reported that only two SNPs in the 17q region were associated with asthma in African American children, and these SNPs were correlated with expression of GSDMB but not ORMDL3 in airway epithelial cells." (PMID 32887352, 2020). "Although various cellular functions of ORMDL3 have been characterized, its precise mechanistic role in altering CD4+ T cell function and enhancing asthma susceptibility has not been resolved." (PMID 33424845, 2020). "The rs2872507 SNP, which influences ORMDL3 gene expression at locus 17q21, may be a possible marker for ICS treatment response in childhood asthma." (PMID 29992143, 2018). "One of the major findings was the identification of the ORMDL3 (ORM1-like protein 3) and the GSDMB (Gasdermin-B) genes within 17q21 locus and CDK12 (Cyclin-dependent kinase 12) as candidate genes for childhood-onset severe asthma." (PMID 29992143, 2018). "Novel interactions between genes were suggested and replicated, such as between ORMDL3 and RORA, where certain genotype combinations gave odds ratios for current asthma of 2.1 (95% CI 1.2-3.6) and 3.2 (95% CI 2.0-5.0) in the BAMSE and PARSIFAL children, respectively." (PMID 24260339, 2013). "In conclusion, our data indicate that ATRA facilitates ORMDL3 production probable through PKA/CREB, and this may be a starting point for more detailed mechanism researches on ATRA and asthma." (PMID 24204796, 2013). "ORMDL3 expression in ASM thus induces changes in ASM (hypertrophy, hyperplasia, increased contractility), which may explain the contribution of ORMDL3 to the development of AHR in childhood onset asthma." (PMID 40131902, 2025). "The differential expression of ORMDL3 was compared with patients without asthma disease." (PMID 40161025, 2025). "However, the exact involvement of ORMDL3 in the development of asthma is still not completely understood." (PMID 38715613, 2024). "In addition to its effects independent of inflammation, ORMDL3 also influences asthma by modulating T cell function." (PMID 36837831, 2023). "Importantly, ORMDL3 is expressed on lung, pancreas and kidney, and notably, one study reported that ORMDL3 enhanced the replication of HRV in cultured human lung epithelial cells, suggesting a potential role in viral-induced asthma AEs." (PMID 35316427, 2022). "Surprisingly, while several mouse studies substantiated a role of ORMDL3 in asthma pathogenesis, another study demonstrated that although knockdown of Ormdl3 increased systemic ceramide levels, it did not alter experimental asthma." (PMID 33939982, 2021). "However, the functional role of ORMDL3 in asthma has not as yet been fully elucidated, and it is not known how this molecule contributes to disease pathophysiology." (PMID 27623174, 2017).
asthma (continued). "Our data presented a new potential side effect of Vitamin A application on asthma control because the major metabolite of Vitamin A, ATRA, promoted ORMDL3 production in both mouse and human cell lines, and this may become a starting point for more detailed mechanism researches on ATRA and asthma." (PMID 24204796, 2013). "Thus, ORMDL3 expression in CD4+ cells may be very important for enhancing Th2 responses in childhood asthma but may not be the key cell expressing ORMDL3, implicating it in the onset of asthma in childhood." (PMID 33661765, 2021). "We reasoned that although ORMDL3 levels may not affect the production of IL-6 or IL-8 cytokines, perhaps they were impacting gene expression of other important immune genes, such as IL-33, IL-25 and TSLP, which have all been implicated in asthma pathogenesis." (PMID 23369242, 2013). "MUC5B, ORMDL3, MUC5AC, CHI3L1, CLCA1, and IL-33 displayed a high non-specific relationship with allergic and nonallergic asthma." (PMID 33936056, 2021). "A very recent GWA study of severe asthma in Europeans found strong evidence for two previously established loci (ORMDL3/GSDMB and IL1RL1/IL18R1) in patients with severe asthma but did not identify any novel loci." (PMID 23028483, 2012). "ORMDL3 expression in ASM thus induces changes in ASM (hypertrophy, hyperplasia, and increased contractility), which may explain the contribution of ORMDL3 to the development of AHR in childhood onset asthma but not to the development of allergic rhinitis." (PMID 33661765, 2021).